BTK (Bruton tyrosine kinase)
Diseases named in the same sentence as BTK in open-access papers (continued):
Sharing a sentence is not in itself a finding about the gene and the disease.
glioma (19 papers, 2017 to 2024). A benign or malignant brain and spinal cord tumor that arises from glial cells (astrocytes, oligodendrocytes, ependymal cells). "BTK has been associated with blood malignancies, and recently with several solid tumours including glioma (reviewed in reference 35)." (PMID 34645618, 2021). "Recently, high expression of BTK was associated with glioma tumorigenesis and found to be a potentially novel prognostic marker for poor survival in patients with glioma." (PMID 34784299, 2021). "Recently, high expression of BTK was associated with glioma tumorigenesis and found to be a novel prognostic marker for poor survival in patients with glioma." (PMID 30733667, 2019). "We also found that high BTK expression levels were associated with poor prognosis in patients with lower grade glioma using TCGA LGG dataset." (PMID 28946903, 2017). "Given the relevance and frequency of ATRX mutations in high-grade glioma patients, we sought to validate the effect of BTK, STAT3, and RTK inhibitors in glioma cell lines derived from adult malignant glioma (MOG-G-UVW and U-251) and pediatric malignant glioma (SF188) patients." (PMID 35406561, 2022). "The fact that high BTK expression levels were associated with poor prognosis in patients with lower grade glioma is in agreement with our data and would suggest that the isoform expressed in glioma is indeed p65BTK." (PMID 34164404, 2021). "In this study, we detail baseline BTK expression in glioma cells and its surrounding vasculature, then measure endothelial junctional expression/function changes with varied ibrutinib doses in vitro." (PMID 38589905, 2024). "It inhibited the glioma cell apoptosis by interacting with BTK and downregulating STAT1 phosphorylation through the facilitation of p300-mediated STAT1 acetylation." (PMID 38962317, 2024). "BTK is highly expressed in clinical glioma samples, and is a prognostic marker and molecular therapeutic target for glioma." (PMID 37576862, 2023). "Only 20% of all astrocytes express BTK, and in human gliomas the BTK expression appears to be restricted to the gamistocytic, or reactive astrocytes." (PMID 36294458, 2022). "We treated MOG-G-UVW, U-251, and SF-188 (EV and ATRX KO) high-grade glioma cell lines with different concentrations (5 μM and 10 μM) of BTK, STAT3, and RTK inhibitors for 48 h in order to assess cell viability." (PMID 35406561, 2022). "Our previous study on glioma revealed that BTK knockdown considerably attenuates tumorsphere formation and enhances the anticancer effects of temozolomide on GBM cells." (PMID 34577576, 2021). "BTK functions as a promising target in solid tumors, including glioma, and its degradation acts as a therapeutic strategy for cancer." (PMID 34784299, 2021). "CPVL suppressed glioma cell apoptosis by physically interacting with BTK and downregulating the STAT1 phosphorylation through promoting p300-mediated STAT1 acetylation." (PMID 34784299, 2021). "In glioma, BTK is considered a cancer cell biomarker, although our data using co-immunofluorescence show that most of the SOX2-positive cancer cells do not express BTK." (PMID 34645618, 2021). "For comparison, in the lower grade glioma, the percentage of BTK and SOX2 co-expression was much higher; however, patient-derived cell models from this lower grade were not available to compare with tissue SOX2 and BTK co-expression." (PMID 34645618, 2021). "Using co-immunofluorescence, we found that only a small proportion of high-grade gliomas express BTK, although this was increased in lower grade gliomas." (PMID 34645618, 2021). "Inhibiting or silencing BTK led to reduced cellular proliferation and migration, induced apoptosis in glioma cell lines and decreased sphere formation and tumourigenesis in xenograft mouse models." (PMID 34645618, 2021). "A previous study reported that BTK was overexpressed in glioma and Ibrutinib suppressed glioma cell growth in vitro and in vivo." (PMID 34164404, 2021).
glioma (continued). "We first used immunohistochemistry from formalin-fixed paraffin-embedded (FFPE) material to assess BTK protein expression in a glioma tissue microarray (TMA) alongside immune cell markers, such as CD163." (PMID 34645618, 2021). "Inhibition of BTK activation with ibrutinib blocks proliferation, migration, and invasion ability of glioma cells in in vitro and in vivo modes." (PMID 34307353, 2021). "In GBM cell lines and mice xenografts, BTK silencing or inhibition results in reduced neurosphere forming ability, migration, and glioma cell proliferation, and induces apoptosis." (PMID 34645618, 2021). "In glioblastoma multiforme (GBM), clinical glioma samples possess increased BTK expression when compared with normal brain cells." (PMID 34307353, 2021). "The correlation of BTK expression with glioma tumorigenesis and with poor survival in glioma patients, and the discovery of a novel oncogenic BTK isoform (p65BTK) in solid tumors, prompted the investigation of the p65BTK expression in gliomas." (PMID 30733667, 2019). "The BTK inhibitor ibrutinib is a promising new therapeutic strategy for glioma, blocking the proliferation, migration and invasion properties and inducing apoptosis and autophagy of glioma cells, targeting the Akt/mTOR pathway." (PMID 30733667, 2019). "Bioinformatics data indicate that BTK is significantly higher in clinical glioma samples compared to normal brain cells, with higher levels of BTK mRNA described in GBM compared with normal brain and astrocyte samples." (PMID 29561760, 2018). "The prognostic significance of BTK expression in glioma has been studied, with high expression of BTK proposed as a novel prognostic marker." (PMID 29561760, 2018). "Taken together, our study suggests that BTK is a novel prognostic marker and molecular therapeutic target for glioma." (PMID 28946903, 2017). "Taken together, our data demonstrate that BTK is required for EGFR-induced NF-κB activation in glioma cells." (PMID 28946903, 2017). "In summary, this is the first report that overexpression of BTK are correlated with poor outcome in almost 50% of glioma patients." (PMID 28946903, 2017). "We found that knockdown of BTK significantly suppressed EGFR-induced NF-κB activation in glioma cells." (PMID 28946903, 2017). "Our data demonstrate that high expression of BTK is a novel prognostic marker for poor survival in patients with glioma." (PMID 28946903, 2017). "Our data demonstrate that high expression of BTK is a novel poor prognostic marker for patients with glioma." (PMID 28946903, 2017). "Our results suggest that BTK is a novel critical mediator of EGFR-induced NF-κB activation in glioma cells." (PMID 28946903, 2017). "The glioma patients expressing high levels of BTK showed statistically poor outcome compared with the low expression group (GSE16011 dataset)." (PMID 28946903, 2017). "BTK-specific inhibitor ibrutinib effectively inhibits the proliferation, migration and invasion ability of glioma cells." (PMID 28946903, 2017). "In the present study, we examined the prognostic significance BTK expression in patients with glioma." (PMID 28946903, 2017). "We then analyzed the mRNA expression of BTK in human normal brain and glioma samples using GEO microarray dataset (GSE16011)." (PMID 28946903, 2017). "High expression of BTK is a prognostic marker for poor survival in patients with glioma." (PMID 35053255, 2022). "Analyzing a large cohort of 71 patients with glial tumors our group found p65BTK expression in 1/5 of cases; notably BTK expression significantly correlates with low-grade tumors (p ≤ 0.05) and OS of patients with grade III gliomas (p ≤ 0.05), suggestive of worst prognosis." (PMID 34164404, 2021). "Finally, across glioma grades, it was interesting to note that BTK protein expression was observed in different cellular compartments; the nucleus in lower grade and/or the cytoplasm in higher grades, and this is consistent with published studies." (PMID 34645618, 2021).
glioma (continued). "Bruton’s tyrosine-kinase (BTK) is a non-receptor tyrosine kinase recently associated with glioma tumorigenesis and a novel prognostic marker for poor survival in patients with glioma." (PMID 30733667, 2019). "The p65BTK is a novel BTK isoform involved in different pathways of drug resistance of solid tumors, thus we aimed to investigate the expression and the putative role of p65BTK in tumors of the central nervous system (CNS)." (PMID 30733667, 2019). "BTK also appeared to be required for EGFR-induced NF-κB activation in glioma cells." (PMID 29561760, 2018). "In this study, we found that high expression of BTK predicts poor outcome of patients with glioma." (PMID 28946903, 2017). "Our data suggest that BTK is up-regulated in a group of glioma patients and may be an important regulator of this disease." (PMID 28946903, 2017). "BTK is required for EGFR-induced NF-κB activation in glioma cells." (PMID 28946903, 2017). "The expression of BTK is higher in glioma than normal samples." (PMID 28946903, 2017). "However, BTK inhibition markedly prevented the EGF-induced nuclear accumulation of p65 in glioma cells." (PMID 28946903, 2017). "In this study, we examined the prognostic significance BTK expression in patients with glioma." (PMID 28946903, 2017). "BTK expression was significantly higher in glioma than normal samples." (PMID 28946903, 2017). "Furthermore, BTK inhibition suppresses the proliferation of glioma cells in vitro and in vivo, and abolishes the EGFR-induced NF-κB activation." (PMID 28946903, 2017). "Collectively, these results indicate that BTK/mTOR inhibition improves tumor response and may serve as the basis for clinical trials testing acalabrutinib/rapamycin combination therapy for patients with high-grade gliomas." (PMID 34577576, 2021). "Whether IDH-mutant gliomas express more BTK needs to be further investigated with more cases." (PMID 34645618, 2021). "However, the role of BTK within the nucleus in glioma needs further investigation." (PMID 34645618, 2021). "Among these seven validated hits, we further characterized the inhibitors targeting BTK (ibrutinib), STAT3 (niclosamide), and RTK (pazopanib), as previous studies have indicated the potential of these drugs to treat high-grade glioma." (PMID 35406561, 2022). "We also observed co-expression of BTK with CD163 and CD68 in a proportion of cells from high-grade glioma tissues." (PMID 34645618, 2021). "Co-immunofluorescence (co-if) was therefore performed to further examine the extent of BTK, SOX2, and CD163 co-expression within individual cells in GBM and a low-grade glioma." (PMID 34645618, 2021). "We found a significant correlation between BTK expression and low-grade (LG) tumors (p ≤ 0.05) and overall survival (OS) of patients with grade III gliomas (p ≤ 0.05), suggestive of worst prognosis." (PMID 30733667, 2019). "The analysis of BTK expression in the whole group of low grade (II WHO) and high grade (III-IV WHO) gliomas demonstrated that p65BTK (BTK+) is significantly more expressed in low grade (II WHO) gliomas (p ≤ 0.05)." (PMID 30733667, 2019). "Glioma stem cell (GSC) lines, isolated from glioblastoma multiforme (GBM), were treated with different concentrations of ibrutinib, a specific inhibitor of BTK, in order to evaluate their metabolic activity, mitotic index and mortality." (PMID 30733667, 2019). "More importantly, BTK inhibition effectively blocked both baseline and EGFR-induced activation of NF-κB pathway mediating glioma cell proliferation and survival." (PMID 28946903, 2017). "In present study, we found that BTK inhibition can significantly block the degradation of IκBα and prevent the nuclear accumulation of NF-κB p65 subunit induced by EGF in glioma cells." (PMID 28946903, 2017). "More importantly, we found that BTK inhibition significantly blocks the degradation of IκBα and prevents the nuclear accumulation of NF-κB p65 subunit induced by EGF in glioma cells." (PMID 28946903, 2017).
glioma (continued). "We next assessed the extent of co-expression of BTK and CD163 antibodies in a high-grade glioma." (PMID 34645618, 2021). "Collectively, our study demonstrates that CPVL directly interacts with BTK to downregulate the STAT1 phosphorylation through promoting p300-mediated STAT1 acetylation, supporting the pursuit of CPVL as a potential target for glioma intervention." (PMID 34784299, 2021). "We would therefore not consider BTK as a robust glioma tumour biomarker, particularly not for high-grade IDH wild-type GBMs." (PMID 34645618, 2021). "To explore the role of p65BTk in gliomas, we cultured glioma stem cell (GSC) lines from patients affected by glioblastoma and evaluated their metabolic activity, mitotic index and mortality after exposure to ibrutinib, a selective potent BTK inhibitor." (PMID 30733667, 2019). "Even though in many cases (such as glioma and glioblastoma, oesophageal and gastric cancers, renal cell and ovarian carcinoma) the isoform of the BTK expressed was not fully investigated and has been assumed to be p77, other reports pointed out the existence of different isoforms." (PMID 31200752, 2019). "The EGFR-induced NF-κB activation may be attributable to BTK pathways—however this is not currently clear given the molecular mechanism of EGFR induced activation of NF-κB in glioma is currently unclear." (PMID 29561760, 2018). "BTK was highly expressed in glioma samples compared with non-tumorous brain tissues." (PMID 28946903, 2017). "In addition, they investigate the expression profile of BTK in human normal brain and glioma samples using GEO microarray dataset (GSE16011) which do not distinguish between the two isoforms, given that the probe set used for BTK spans all over the mRNA length." (PMID 34164404, 2021). "While BTK was overexpressed in 14 hematopoietic tumors, CDK6 was overexpressed in both hematopoietic and nonhematopoietic tumors, including neuroblastoma and glioma." (PMID 31651965, 2019). "However, a significant correlation between OS and BTK+ was found in the subgroup analysis of patients with grade III gliomas (p ≤ 0.05); in patients with grade IV gliomas, BTK+ also correlates with worst prognosis although without significant correlation (p = 0.36)." (PMID 30733667, 2019).
non-Hodgkin lymphoma (19 papers, 2013 to 2025). Distinct from Hodgkin lymphoma both morphologically and biologically, non-Hodgkin lymphoma (NHL) is characterized by the absence of Reed-Sternberg cells, can occur at any age, and usually presents as a localized or generalized lymphadenopathy associated with fever and weight loss. "Selinexor is currently in a phase 1 trial in combination with the BTK inhibitor (BTKi) ibrutinib for patients with relapsed/refractory CLL or aggressive non-Hodgkin lymphoma (NCT02303392)." (PMID 37528310, 2023). "Inhibition of BTK is a novel mechanism to treat non-Hodgkin’s lymphoma, and ibrutinib does this by forming an irreversible covalent bond with BTK at the Cys 481 site." (PMID 25724156, 2015). "In one study, excellent response rates could be demonstrated in certain non-Hodgkin lymphoma subtypes, however, issues related to the development of resistance to BTK inhibitors need to be addressed." (PMID 32211398, 2020). "B-cell receptor (BCR) signaling pathway inhibitors (including Bruton’s tyrosine kinase [BTK] inhibitors, and phosphatidylinositol-3 kinase inhibitors [PI3Ki]) have shown clinical efficacy in non-Hodgkin lymphoma (NHL)." (PMID 33328591, 2021). "NX-2127, developed by Nurix Therapeutics, is an oral BTK degrader currently under evaluation in Phase 1 clinical trials for B-cell malignancies, including chronic lymphocytic leukemia (CLL) and non-Hodgkin’s lymphoma (NHL)." (PMID 40574056, 2025). "Bruton’s tyrosine kinase (BTK) inhibitors, such as ibrutinib, zanubrutinib, and acalabrutinib, are used to treat non-Hodgkin lymphoma, among other hematologic malignancies and inflammatory diseases." (PMID 39687072, 2024). "Nemtabrutinib is a promising BTK inhibitor with potent activity against B-cell malignancies, including CLL and non-Hodgkin lymphoma (NHL)." (PMID 38138527, 2023). "We would advocate for the clinical trials comparing traditional chemo-immunotherapy with Bendamustine/Rituximab in combination with Bruton's tyrosine kinase (BTK) inhibitors, as was recently examined in a Phase 1/1b trial for untreated and relapsed/refractory non-Hodgkin lymphoma." (PMID 27119356, 2016).
Arthritis (18 papers, 2013 to 2026). Inflammation of a joint. "In the model of arthritis, BTK-deficient mice and BTK inhibitor-treated rodents showed reduced RA progression." (PMID 34650569, 2021). "Apart from the manifestation of tuberculosis, some patients with BTK mutation affecting the kinase or SH2 domain exhibited other inflammatory conditions such as abscesses (n=7), cellulitis (n=4), arthritis (n=3), cholecystitis (n=1), and ulcers (n=1)." (PMID 37809070, 2023). "Another selective BTK inhibitor, CGI1746, has been reported to reduce CCL2 levels from macrophages in myeloid cell‐dependent arthritis by blocking trans‐phosphorylation of BTK Tyr551 and subsequent auto‐phosphorylation at Tyr223." (PMID 34897650, 2022). "Commensal microbes and intact BTK signaling have been independently shown to be essential for arthritis development in K/BxN mice." (PMID 35422819, 2022). "The correlation between clinical arthritis score and BTK phosphorylation as a PD marker was analyzed, and moderately positive correlations with correlation coefficients of 0.6750, 0.7795 and 0.8603 were observed at 4, 12 and 24 h, respectively (left)." (PMID 34548595, 2021). "In contrast to the poor clinical success rate of BTK inhibitors for treating RA, nearly all have reported positive results in animal models of arthritis." (PMID 34803999, 2021). "The most common in vivo model employed BTK inhibitor characterization was in mouse and rat arthritis models and was reported by 9 of the 13 clinical BTK inhibitors." (PMID 34803999, 2021). "In the context of CHIKV-induced arthritis in patients, it is interesting to note that BTK is involved in osteoclastogenesis and the inhibition of BTK on bone resorption is protective." (PMID 31461898, 2019). "Using a collagen-induced arthritis model, newer understanding of BTK function with inhibitors (CGI1746) for B cell or myeloid cell-driven diseases is generating compelling evidence and rationale for targeting BTK in RA." (PMID 28265691, 2017). "In the arthritis model tissues, the BTK and JAK3 signaling pathways were activated." (PMID 40626319, 2025). "Another association of BTK to disease (arthritis) via the CXCL12 signaling pathway can be seen by BTK’s involvement in mediating osteoclast differentiation and bone resorption activity in a CIA mouse model that can be blocked by an antagonist to BTK." (PMID 34803999, 2021). "Recently, dual BTK/JAK3 inhibitors have drawn extensive attention in the fields of cancer and arthritis treatment." (PMID 40626319, 2025). "Dose-dependent efficacy of other BTK inhibitors such as PCI-32765 and GDC-0834 has been demonstrated in animal models of arthritis." (PMID 28265691, 2017). "Mechanistically, Wj1113 inhibits BTK/JAK3 signaling in vivo and alleviates arthritis in joints." (PMID 40626319, 2025). "Although it was previously shown that BTK in myeloid cells was not necessary for arthritis in the K/BxN serum transfer model, this question has not been tested in the more robust spontaneous K/BxN model." (PMID 35422819, 2022).